EPHA2 (EPH receptor A2)
Diseases named in the same sentence as EPHA2 in open-access papers (continued):
Sharing a sentence is not in itself a finding about the gene and the disease.
gastric cancer (continued). "To investigate the impact of EphA2 targeting on clinically relevant models of gastric cancer, we built a PDX mouse model from tissues from four gastric cancer patients." (PMID 30451837, 2018). "Upon inhibition of endogenous EphA2, the number of SGC-7901/L-OHP oxaliplatin-resistant gastric cancer cells migrating through the Matrigel significantly decreased compared with the control group (P < 0.05)." (PMID 28624791, 2017). "The current study was designed to establish the oxaliplatin-resistant human gastric cancer cell line SGC-7901/L-OHP, to determine if EMT in these cells could be reversed, and to determine if the susceptibility of these cells to oxaliplatin was affected by silencing EphA2 expression." (PMID 28624791, 2017). "EphA2 upregulation is a common event in gastric cancer specimens and is closely correlated with cancer metastasis and the promotion of EMT in gastric cancer cells through activation of Wnt/β-catenin signaling." (PMID 28624791, 2017). "While established mechanisms of OXA resistance in gastric cancer involve JUNB-mediated MAPK hyperactivation, EphA2-induced EMT, METTL3-dependent DNA repair/stemness maintenance, and LINC00641-regulated autophagy, our study reveals a distinct immunosuppressive axis mediated by OASL." (PMID 41271618, 2025). "In addition, it has been demonstrated that EphA2 activates ANXA2 by phosphorylating the Tyr426 site of YES1, which in turn promotes the proliferation, migration and invasion of gastric cancer cells." (PMID 39050762, 2024). "Both in vivo and in vitro experiments showed that C1GALT1 promotes EPHA2 phosphorylation and Ephrin A1-mediated cell migration by regulating the O-glycosylation of EPHA2, suggesting that C1GALT1 may be a potential therapeutic target for gastric cancer." (PMID 36429094, 2022). "EphA2 could activate Wnt/beta‐catenin and Hippo signalling pathways, which in turn induced EMT and downstream signalling cascade, thus mediating tumour invasiveness and resistance to cancer therapeutics in gastric cancer." (PMID 33586348, 2021). "One gastric cancer patient showed a partial response and 13 patients achieved stable disease, although the latter did not correlate with EphA2 expression in tumor biopsies, suggesting this may not be treatment-related." (PMID 32397088, 2020). "Gene expression or quantitative assessment is important and necessary to confirm the outcomes of this study, although mRNA expression levels of EphA2, EphA4, and ephrinA1 were shown to be higher in gastric cancer tissue than in non-cancerous gastric tissue by other investigators." (PMID 23738943, 2013). "EphA2 was not a significant prognostic factor in stage II and III gastric cancer." (PMID 23738943, 2013).
colorectal cancer (48 papers, 2013 to 2026). A primary or metastatic malignant neoplasm that affects the colon or rectum. "To evaluate this approach, we selected the kinase domain of EPHA2, a receptor tyrosine kinase implicated in colorectal cancer progression and an important target for therapeutic inhibitor development." (PMID 41739268, 2026). "In the comparison between the histopathological data of colorectal cancer and serum EphA2 levels, higher EphA2 levels were observed to be associated with a larger tumor size and greater depth of invasion." (PMID 39766211, 2024). "The co-expression of EGFR and FGFR2 linked to resistance to EGFR kinase inhibitors in esophageal cancer was reported, while the co-expression of EGFR and EPHA2 was found associated with the promotion of tumorigenesis in lung and colorectal cancer." (PMID 38338684, 2024). "The cell signaling factors EGFR, EphA2, and Ephexin1 are associated with lung and colorectal cancer and play an important role in tumorigenesis." (PMID 35668076, 2022). "EphA2 is highly expressed in colorectal cancer cells and causes high invasiveness and metastasis of cells, and poor prognosis." (PMID 33712565, 2021). "As in the case of EphA1 and EphA2, initial upregulation of EphB2 and EphB3 expression appears to be followed by a loss of expression in the more advanced metastatic stages of colorectal cancer." (PMID 33430066, 2021). "EPHA2 overexpression in colorectal cancer is associated with advanced stage tumors, metastatic disease and higher microvessel counts." (PMID 25193853, 2014). "Confirmation of the activation of EPH signaling mediated by EPHA2 point mutations in colorectal cancer is of upmost importance considering the availability of FDA approved drugs targeting this receptor, such as Dasatinib." (PMID 25193853, 2014). "Indeed, EphA2 has been linked to colorectal cancer development as targeted EphA2 gene disruption was found to reduce intestinal tumorigenesis in the APC/Min + mouse model." (PMID 27246245, 2016). "This analysis showed variable expression of EphA2 across different human cancer types, with notably high expression in pancreatic, bladder, and colorectal cancers, and low expression in lung, breast, prostate, and lymphoma." (PMID 40225586, 2025). "We calculated the cutoff value for serum EphA2 in healthy individuals and patients with colorectal cancer." (PMID 39766211, 2024). "EPHA2 was found to promote the formation of vasculogenic mimicry (VM) in colorectal cancer (CRC) via PI3K/AKT/mTOR and ERK1/2 signaling, and TNF plays a role in angiogenesis by synergistically inducing VEGF production with IL-1beta (IL1B)." (PMID 39596139, 2024). "In this study, we confirmed the feasibility of measuring EphA2 released into the extracellular space over time using colorectal cancer cell lines." (PMID 39766211, 2024). "In the future, EphA2 expression has the potential to be applied for the treatment of colorectal cancer." (PMID 39766211, 2024). "As the significance of EphA2 in colorectal has been elucidated, it is expected that EphA2 will become a useful biomarker for the early detection and personalized treatment of colorectal cancer." (PMID 39766211, 2024). "We found that serum EphA2 levels were significantly elevated in patients with Stage I colorectal cancer compared to healthy individuals." (PMID 39766211, 2024). "Then, we assessed the protein expression levels of EphA2 in normal and colorectal cancer tissues by tissue samples from the Human Protein Atlas database." (PMID 37980165, 2023). "Here, we found that EphA2 was abnormally highly expressed in colorectal cancer and that patients with colorectal cancer with high EphA2 expression had a worse prognosis." (PMID 37980165, 2023). "Here, we found that EphA2 was abnormally highly expressed in colorectal cancer tissues, and patients with high EphA2 expression had a worse prognosis." (PMID 37980165, 2023).
colorectal cancer (continued). "In this study, we found that EphA2 was abnormally highly expressed in colorectal cancer and that patients with high expression had a worse prognosis." (PMID 37980165, 2023). "Together, these results suggest a link between lung and colorectal cancers and the expression of Ephexin1, EphA2 and EGFR, and the possibility that these proteins interact with each other, either directly or indirectly." (PMID 35668076, 2022). "We then used PLA analysis to look for in vivo interactions between EGFR and EphA2 in both normal and cancerous cells using lung and colorectal cancer patient tissues." (PMID 35668076, 2022). "Here, we showed that Ephexin1, EphA2, and EGFR are each expressed at higher levels in lung and colorectal cancer patient tissues, and binding of EGFR to EphA2 was associated with both increased tumor grade and metastatic cases in both cancer types." (PMID 35668076, 2022). "In the present study, we found that the expression of EGFR, EphA2, and Ephexin1 was upregulated and correlated to lung and colorectal cancers." (PMID 35668076, 2022). "In the last decades, they have emerged as key players in solid tumors, including colorectal cancer (CRC); however, what causes EphA2 to switch between tumor-suppressive and tumor-promoting function is still an active theater of investigation." (PMID 33572284, 2021). "Many studies have observed an altered expression of Eph receptors in colorectal cancers, especially for EphA2, EphA1, EphB4, and EphB2." (PMID 32316101, 2020). "EphB2 and EphA2 control stemness and differentiation in the intestinal mucosa, but the way they cooperate with the complex mechanisms underlying tumor heterogeneity and how they affect the therapeutic outcome in colorectal cancer (CRC) patients, remain unclear." (PMID 30501625, 2018). "In conclusion, both EphA2 and EphB4 show potential as target for image-guided colorectal cancer surgery, but EphB4 seems to have the best characteristics with respect to tumor/normal mucosa distribution, as shown in a relatively large cohort of 168 patients." (PMID 28165374, 2017). "To explore if a role for TF-EphA2 cross-talk in this context is plausible we stained a cohort of colorectal cancer specimens for TF and EphA2 by IHC and scored their expression levels in tumor cells." (PMID 27246245, 2016). "TF expression was, for both primary cancers and metastases, found in a minority of cases, and our results indicate that TF and EphA2 co-expression is an event that occurs in a subset of colorectal cancers that are characterized by low differentiation." (PMID 27246245, 2016). "Expression of TF and EphA2 in human colorectal cancer specimens was examined by immunohistochemistry." (PMID 27246245, 2016). "EphA2 and TF were co-expressed in a cohort of human colorectal cancer specimens, providing evidence that the prerequisites for TF–EphA2 cross-talk in vivo are present." (PMID 27246245, 2016). "In turn, the EphA2 gene expression in advanced stage colorectal cancer is at a lower level than in LSC tissues which can be explained by the increased importance of this gene in the initiation of tumor development." (PMID 27110571, 2016). "EphA2 is aberrantly overexpressed in colorectal cancer and can form LLPS condensates on the cell membrane, which is positively correlated with the expression of ferroptosis‐related genes and immune cell infiltration, contributing to colorectal cancer progression." (PMID 40211955, 2025). "have found that EphA2 (Erythropoietin-producing hepatocellular A2, EphA2) could be involved in the advancement of colorectal cancer by forming LLPS condensates and further affecting the immune cell infiltration." (PMID 40104511, 2025). "EphA2 expression was consistently observed across all these colorectal cancer cell lines." (PMID 39766211, 2024). "If soluble EphA2 levels in the serum can be used in colorectal cancer patients, it could provide a more convenient and less invasive method for their diagnosis and treatment." (PMID 39766211, 2024).
colorectal cancer (continued). "The early detection of elevated EphA2 levels may enable timely intervention, potentially improving outcomes for colorectal cancer patients." (PMID 39766211, 2024). "To explore the relationship between EphA2 and ferroptosis, we first analysed differential gene expression in samples with differential EphA2 expression using TCGA colorectal cancer samples, and in total we identified seven up-regulated and 92 down-regulated genes." (PMID 37980165, 2023). "In addition, we found that EphA2 expression in colorectal cancer was positively correlated with the expression of ferroptosis-related genes and the infiltration of multiple immune cells." (PMID 37980165, 2023). "In colorectal cancer, m6A methylated EphA2 promotes vasculogenic mimicry via PI3K/Akt signaling." (PMID 37858219, 2023). "Furthermore, we analyzed the correlation between EphA2 expression and the expression of common ferroptosis-related genes in colorectal cancer and found that EphA2 expression was significantly correlated with the expression of several ferroptosis-related genes." (PMID 37980165, 2023). "Similarly, for colorectal cancer patients, higher expression of Ephexin1 and EphA2 correlated to worse survival rates, and lower expression of EphA3 correlated to worse survival rates." (PMID 35668076, 2022). "Our results indicate that the formation of a complex between EGFR, EphA2, and Ephexin1 plays an important role in lung and colorectal cancers, and that inhibition of this complex may be an effective target for cancer therapy." (PMID 35668076, 2022). "To investigate the importance of Ephexin1, EGFR and EphA2 in lung and colorectal cancer patient tissues, we analyzed the TMA database for lung and colorectal tissues composed of carcinomas and metastatic tumors of different grades to determine the expression levels of each of the three proteins." (PMID 35668076, 2022). "In addition, EphA2 expression is associated with EGFR inhibitor-resistant lung cancer cells, and combined treatment of EGFR and EphA2 targeted therapy is more effective than monotherapy in colorectal cancer and lung cancer." (PMID 35668076, 2022). "As for its upstream miRNAs, EPHA2 has been indicated to be targeted by different miRNAs to participate the development of various cancers, including non-small cell lung cancer, hepatocellular carcinoma as well as colorectal cancer." (PMID 33087088, 2020). "EphA2 and EphB4 are known to be upregulated, particularly in the early stages of colorectal cancer." (PMID 28165374, 2017). "Interestingly, earlier studies using Q-PCR to analyze 53 paired normal and colorectal cancer samples showed that EphB4 is more significantly overexpressed in tumor tissue compared to normal tissue than EphA2." (PMID 28165374, 2017). "TF and EphA2 were expressed in colorectal cancer specimens, and were significantly correlated." (PMID 27246245, 2016). "However, high levels of both TF and EphA2 are recognized events in malignant cells, and we used a colorectal cancer material to show that co-expression of TF and EphA2 indeed occurs in vivo." (PMID 27246245, 2016). "We also found that cell lines express on average 11 druggable mutations, including frequent mutations (>20%) in the receptor tyrosine kinases AXL and EPHA2, which have not been previously considered as potential targets for colorectal cancer." (PMID 25193853, 2014). "Since EGFR, EphA1, and EphA2 positively correlated with Ephexin1 in both colon and lung tissues, we focused on these three proteins and analyzed the survival rates of lung cancer and colorectal cancer patients relative to the expression levels of all four proteins." (PMID 35668076, 2022). "Interestingly, EphA2 is highly expressed in a variety of cancers, including breast, lung, prostate, urinary bladder, ovarian, esophageal, pancreatic, and colorectal cancer." (PMID 23738943, 2013).
colorectal cancer (continued). "IGF2BP2 and IGF2BP3 enhanced the stability of methylated ephrin type-A receptor 2 (EPHA2) and vascular endothelial growth factor A (VEGFA) mRNAs, respectively, in colorectal cancer cells." (PMID 38503745, 2024). "We analysed the correlation between EphA2 expression and MSI and TMB using TCGA colorectal cancer data and found a significant positive correlation between EphA2 expression and MSI and TMB scores." (PMID 37980165, 2023). "EphA2 is a poor prognostic marker in stage II/III CRC and can promote cell migration and invasion in colorectal cancer." (PMID 35596224, 2022). "In conclusion, Ephexin1 is proposed as an effective target protein for the therapy of tumors in lung and colorectal cancers since it plays an important role in regulating interactions between EGFR and EphA2." (PMID 35668076, 2022). "In such a frame, we detail the interaction of the EphA2 and EGFR pathway in solid tumors, including colorectal cancer." (PMID 33572284, 2021). "In this study, EphA2 and EphB4 are evaluated as targets for IGOS of colorectal cancer by immunohistochemistry (IHC) using a tissue microarray (TMA) consisting of 168 pairs of tumor and normal tissue." (PMID 28165374, 2017). "UBE4A-SLAP has been shown to ubiquitylate EphA2 in cells and in vitro, and knockdown of SLAP or of UBE4A slightly increased total EphA2 protein in colorectal cancer cell lines." (PMID 28883622, 2017). "Human HCT116 colorectal cancer cells were treated with 0-300 nM NW457 for 24 h or 48 h, respectively, and the expression levels of ephrin A2 (EPHA2) and epidermal growth factor receptor (EGFR) were measured by FACS surface staining." (PMID 27259245, 2016). "Interestingly, annotation scores for TF and EphA2 expression correlated (Spearman Rho 0.48, p < 0.001), with 87 % of TF positive primary tumors and 100 % of TF positive metastases also being positive for EphA2, demonstrating that TF and EphA2 are co-expressed in colorectal carcinomas." (PMID 27246245, 2016). "Primeaux V., with co-authors, demonstrated that CLDN1 regulates ephrin type-A receptor 2 (EPHA2), a tyrosine kinase, which activates the AKT signaling pathway and regulates CD44 expression in colorectal cancer (CRC) cells, thereby promoting the stemness of CRC and chemoresistance." (PMID 40943068, 2025). "As an E3 ubiquitin ligase, only two experimentally validated substrates of RNF149 were reported so far: wild-type but not mutant BRAF in colorectal cancer, and EPHA2 in NPC." (PMID 37958377, 2023). "In addition, we also found that EphA2 can undergo phase separation and a positive correlation with the expression of ferroptosis-related genes and immune cell infiltration, but whether other members of the Eph receptor family have similar phenomena in colorectal cancer requires further evidence." (PMID 37980165, 2023). "Presented genes, especially ADAM17, MMP9, EphA2, TIMP1, ICAM 11, and CD4, may be used as prognostic markers of advanced stages of colorectal cancer, contributing to the development of new lines of therapy focused on reducing metastasis of the primary tumor." (PMID 27110571, 2016). "Point mutations in EPHA2 and EPHA1 have not so far been described in the literature for colorectal cancer." (PMID 25193853, 2014). "In colorectal cancer, EphA2 and EphB2, belonging to the tyrosine kinase receptor family, have been identified as novel markers for colorectal CSCs, whose expression is strongly correlated with the expression of CD44 and Lgr5, as well as the stemness of colorectal cancer cells." (PMID 41346572, 2025). "However, the authors found no other reports documenting increasing EphA2 gene expression primarily in the early stages of colorectal cancer." (PMID 27110571, 2016). "In addition, EPHA2-FC soluble receptors were shown to significantly reduce tumor volume and overall metastatic burden in pre-clinical models of breast and pancreatic tumors, but have not been evaluated in colorectal cancer models." (PMID 25193853, 2014).